CAT (catalase)
Description:
Catalyzes the degradation of hydrogen peroxide (H(2)O(2)) generated by peroxisomal oxidases to water and oxygen, thereby protecting cells from the toxic effects of hydrogen peroxide. Promotes growth of cells including T-cells, B-cells, myeloid leukemia cells, melanoma cells, mastocytoma cells and normal and transformed fibroblast cells.
Tractability: Small molecule: a structure with a bound ligand is known; it has a high-quality binding pocket. Antibody: its Gene Ontology location is reachable by antibodies, with high confidence. PROTAC: ubiquitination databases record sites on it; its protein half-life has been measured; a small molecule that binds it is known.
Target class: Enzyme; Oxidoreductase
Safety:
Unwanted effects reported when the protein is acted on. In parentheses: how it was acted on, where the effect was seen, and who reports it.
cardiac damage after anthracycline exposure (source: ClinPGx)
Gene: Protein-coding gene on chromosome 11 (34,438,906 to 34,472,061, forward strand). Ensembl gene ENSG00000121691.
Subcellular location: Peroxisome matrix
Subcellular location (Human Protein Atlas): Vesicles
Pathways (Reactome):
Cellular responses to stimuli: Detoxification of Reactive Oxygen Species; Mitochondrial unfolded protein response (UPRmt)
Gene expression (Transcription): FOXO-mediated transcription of oxidative stress, metabolic and neuronal genes
Immune System: Neutrophil degranulation
Protein localization: Peroxisomal protein import
Gene Ontology:
Molecular function: antioxidant activity; catalase activity; enzyme binding; heme binding; identical protein binding; NADP binding; protein homodimerization activity; oxidoreductase activity, acting on peroxide as acceptor; aminoacylase activity
Biological process: cellular detoxification of hydrogen peroxide; hydrogen peroxide catabolic process; negative regulation of apoptotic process; osteoblast differentiation; response to reactive oxygen species; UV protection; cellular response to growth factor stimulus; kidney development; response to activity; response to amitrole; response to cadmium ion; response to estradiol; response to ethanol; response to fatty acid; response to hyperoxia; response to hypoxia; response to inactivity; response to insulin; response to L-ascorbic acid; response to lead ion; response to light intensity; response to oxidative stress; response to ozone; response to phenylpropanoid; response to toxic substance; and 5 more
Cellular component: catalase complex; extracellular exosome; focal adhesion; membrane; peroxisomal matrix; peroxisome; protein-containing complex; cytosol; extracellular region; ficolin-1-rich granule lumen; mitochondrion; peroxisomal membrane; secretory granule lumen
Genetic constraint (gnomAD): Loss-of-function variants: 35 observed, 51.54 expected, observed/expected ratio (o/e) 0.68, 90% interval 0.52 to 0.9. The upper end of that interval is the gene's LOEUF score, 0.9, which puts it in group 3 of 6, group 1 being the genes least tolerant of losing a copy. Missense variants: 611 observed, 647.18 expected, observed/expected ratio (o/e) 0.94, 90% interval 0.88 to 1.01. Synonymous variants: 201 observed, 222.66 expected, observed/expected ratio (o/e) 0.9, 90% interval 0.8 to 1.01.
Gene-disease validity (ClinGen):
ClinGen rates the evidence that CAT causes each of these diseases.
acatalasia (autosomal recessive): Moderate. A congenital disorder resulting from a deficiency in erythrocyte catalase, an enzyme responsible for the breakdown of hydrogen peroxide.
Homologues: Orthologues: chimpanzee CAT (99% identical), macaque CAT (94% identical), dog CAT (92% identical), pig CAT (91% identical), guinea pig CAT (90% identical), mouse Cat (89% identical), rat Cat (89% identical), rabbit CAT (88% identical), tropical clawed frog cat.2 (82% identical), tropical clawed frog cat (78% identical), zebrafish cat (78% identical), tropical clawed frog cat.3 (72% identical), and 5 more.
Diseases named in the same sentence as CAT in open-access papers:
CAT is named in the same sentence as 726 diseases in open-access papers, as found by Europe PMC text mining. Sharing a sentence is not in itself a finding about the gene and the disease. The quoted sentences say what the papers report.
diabetes (409 papers, 2001 to 2026). "Meanwhile, viruses prevented the synthesis of SOD, GPx, and CAT, leading to redox imbalance and cellular oxidative stress, thereby activating the immune response and causing chronic diseases such as diabetes mellitus and autoimmune diseases." (PMID 40423420, 2025). "- GA regulated lipid peroxidation (measured by TBARS) and antioxidant enzymes (GPX, superoxide dismutase, and catalase) in the liver and kidney, which are affected by diabetes-related complications caused by hyperglycemia." (PMID 39199245, 2024). "In fact, CAT deficiency has been suggested to predispose to progressive pancreatic β-cell failure and diabetes." (PMID 39000039, 2024). "STZ-induced type 2 diabetes mellitus is associated with a decrease in catalase expression and a significant reduction in superoxide dismutase activity." (PMID 39065816, 2024). "Humans with low catalase levels are at increased risk for diabetes and altered lipid and carbohydrate metabolism." (PMID 36901407, 2023). "Diabetes is associated with an increase in oxidative stress as shown by an increase in free radicals and decreased activities of catalase (CAT), superoxide dismutase (SOD), glutathione S-transferase (GST), glutathione peroxidase (GPX), and GSH." (PMID 37570720, 2023). "The vanadium (V)-chlorodipicolinate compound caused a statistically significant increase in both CAT and GPx activity in comparison to an animal group with diabetes." (PMID 35269182, 2022). "H2O2 has been shown to damage pancreatic b-cells, which with CAT deficiency leads to the development of diabetes." (PMID 35207512, 2022). "CAT mutations have been reported in the literature regarding autoimmune diseases such as diabetes mellitus or vitiligo and arterial hypertension." (PMID 36555526, 2022). "Research has indicated that diabetes is associated with decreased antioxidant enzyme activity, and we observed reductions in catalase, GPx, and SOD activities in the pancreases of the risperidone-treated HFD-fed mice compared with the control mice." (PMID 33401717, 2021). "Based on various studies, catalase malfunctioning or deficiency is associated with many diseases like diabetes mellitus." (PMID 34946740, 2021). "Deficiency or malfunction of catalase is postulated to be related to the pathogenesis of many age-associated degenerative diseases like diabetes mellitus, hypertension, anemia, and vitiligo." (PMID 34938803, 2021). "In C57BL/6J mice, catalase deficiency also promotes diabetes and has been reported to significantly increase body weight." (PMID 33080438, 2020). "In a review article, CAT polymorphisms were associated with the risk of developing diabetes mellitus since CAT decreased due to other factors such as genetics and environments." (PMID 31171927, 2019). "Catalase deficiency or malfunctioning is associated with many diseases such as diabetes mellitus, vitiligo, cardiovascular diseases, Wilson disease, hypertension, anemia, some dermatological disorders, Alzheimer's disease, bipolar disorder, and schizophrenia." (PMID 31827713, 2019). "Another single nucleotide polymorphism of the CAT gene 111C/T in exon 9 was examined among different forms of diabetes and showed a very poor association." (PMID 31827713, 2019). "Two single nucleotide polymorphisms of CAT gene, viz., 1167T/C and -262C/T, have been reported to have a strong association with type 1 diabetes mellitus." (PMID 31827713, 2019). "While genetic catalase deficiency is associated with diabetes in humans and animals, our data suggests that in the general population, catalase activity is increased, rather than deficient, in adipose tissue of insulin resistant subjects." (PMID 28545081, 2017). "Animal studies demonstrate that genetic deficiency of the H2O2-scavenging enzyme catalase triggers adipose tissue oxidative stress, deterioration of insulin sensitivity and susceptibility to diabetes." (PMID 28545081, 2017).
diabetes (continued). "Diabetes‐induced autophagy was markedly suppressed in diabetic mice with cardiac overexpression of catalase, and this was associated with alleviation of diabetes‐induced cardiac apoptosis, and myocardial hypertrophy and dysfunction." (PMID 28643395, 2017). "This research has shown that diabetes caused a state of brain oxidative stress as evidenced by the decrease in brain catalase activity, decrease in brain GSH content, and increase in brain MDA content." (PMID 26491434, 2015). "Diabetes-linked alterations in antioxidant defense system enzymes, such as catalase, glutathione peroxidase, and superoxide dismutase, have been demonstrated." (PMID 25114929, 2014). "The results demonstrated that diabetes causes a significant elevation in the level of hepatic arylsulfatase B and a significant reduction of hepatic catalase as an antioxidant enzyme." (PMID 25516848, 2014). "Reduced scavenging of free radicals by SOD, decreased glutathione and decreased activity of catalase are associated with diabetes and vascular pathology." (PMID 18477407, 2008). "The decrease in CAT activity is considered to be a cause of OS in diabetes." (PMID 39064844, 2024). "Variants in the antioxidant enzyme catalase are linked to hypertension, dyslipidemia, and diabetes." (PMID 39125390, 2024). "T2DM patients who have the TT genotype in -262 C/T may have elevated risk of diabetes complications; these patients had the lowest mean CAT and HDL, as well as the highest glucose, HbA1 and TCH levels." (PMID 37759451, 2023). "Low concentrations of SOD and CAT may be linked to T2D through OS-induced hyperglycemia in patients with diabetes." (PMID 37432193, 2023). "Additionally, there is evidence that CAT polymorphism is associated with diabetes complications, such as distal symmetric polyneuropathy, nephropathy, retinopathy and risk factors for its development." (PMID 37759451, 2023). "In addition, polymorphisms in the CAT gene and reduced catalase activity have also been associated with several metabolic diseases, such as diabetes, hypertension, and peroxisomal/peroxisomal diseases." (PMID 36439174, 2022). "In this study, the diabetes-related genes in the case of early-onset diabetes with a significant family history were examined, and our results showed the presence of the intron mutations of catalase (CAT) gene and hepatocyte nuclear factor 1β (HNF1β) gene." (PMID 35480487, 2022). "Hereditary catalase deficiencies have been associated with an increased risk of diabetes." (PMID 35685525, 2022). "In a diabetic nephropathy cohort study, CAT is a downregulated gene which may be associated with the regulation of kidney functions in diabetes." (PMID 34367469, 2021). "In our study, treatment of diabetic animals with raspberry fruit extract could reverse the alterations in serum level of NO and MDA, and SOD and CAT activity caused by chemical diabetes induced in animals." (PMID 33907678, 2021). "Hence, it is necessary to have a good understanding of the kinetics parameters of PON1 and catalase to predict their diagnostic relevance as a biomarker in diabetes and to study the effects of treatment with M. oleifera extract." (PMID 32911700, 2020). "The oxidative stress involved in diabetes-associated pathological damages reduces antioxidant enzyme activities (catalase (CAT), superoxide dismutase (SOD), and glutathione peroxidase (GPx)), and octaphlorethol A treatment increased the enzyme activity due to its antioxidant potency." (PMID 33007997, 2020). "Low catalase activity in blood is associated with the diabetes caused by alloxan." (PMID 32911700, 2020). "Deficiency or malfunction of catalase is postulated to be related to the pathogenesis of many age-associated degenerative diseases like diabetes mellitus, hypertension, anemia, vitiligo, Alzheimer's disease, Parkinson's disease, bipolar disorder, cancer, and schizophrenia." (PMID 31827713, 2019).
diabetes (continued). "It was proposed that catalase deficiency may be responsible for the development of diabetes mellitus in an indirect way." (PMID 31827713, 2019). "To clarify this, we aimed to examine the effect of catalase on both diabetes‐associated NF‐κB activation and autophagy and to determine whether there is a mechanistic link between these phenomena." (PMID 28643395, 2017). "Most evidence supports associations between the SOD2 SNP Ala16Val genotype and diseases such as breast, prostate, and lung cancers, diabetes, and cardiovascular disease, whereas the GPx1 SNP Pro197Leu and catalase SNP C-262T SNP genotypes are associated with breast cancer." (PMID 24058721, 2013). "Complete acatalasemia bears severely adverse health outcomes, including diabetes mellitus; lower-than-normal catalase activity implies a high risk of the premature onset of age-related degenerative diseases, and has been proven to be a key metabolic feature in MCS patients." (PMID 21845158, 2011). "Association of the SOD1, SOD2 and CAT polymorphism, BMI, age, duration of diabetes, sex, type of diabetes and SOD activity as independent variables with the presence of microangiopathy or macroangiopathy as dependent variables was performed using a logistic regression model." (PMID 18423055, 2008). "The impairment of the antioxidant balance in pancreatic β cells with reduced catalase expression and increased concentration of hydrogen peroxide has been associated with reduced insulin production, insulin resistance, and the development of type 2 diabetes mellitus." (PMID 40284576, 2025). "Consequently, β-cell compensation could not work efficiently for the decreased insulin sensitivity, which resulted in inducing OS and decreasing CAT activity-linked diabetes." (PMID 37432193, 2023). "However, it was clear that long-term treatment of diabetes with all doses, particularly with a high dose of extract, induced a reversed effect on catalase activity, which may be associated with reduced oxidative stress." (PMID 34285703, 2021). "Consistently, the activity of the antioxidant enzymes CAT, SODs and of GPx has been described as defective in diabetics with complications, and an association in vivo has been found between reduced GPx activity and increased risk of cardiovascular complications in diabetes." (PMID 27137793, 2016). "Even short-term activation of PPAR-γ by RSG reduces NAD(P)H oxidase and enhances catalase activity causing a reduction of superoxide and hydroxyl radical production, thereby enhancing NO mediation of coronary vasodilation and reducing lipid peroxidation in diabetes." (PMID 22829806, 2012). "The levels of serum glucose, HbA1c, pancreatic tissue MDA, TNF-α, and IL-1β were increased in the diabetes group when compared with the control and DM group, while serum insülin level, CAT, and SOD activities were lower in the diabetes group." (PMID 42254432, 2026). "In a diabetes mellitus model, agmatine treatment has been demonstrated to elevate GPx and catalase levels in leukocytes and to reduce oxidative/nitrosative stress." (PMID 41557172, 2026). "Concurrently, the diurnal oscillations of all antioxidant enzymes (T-AOC, T-SOD, GSH-Px, and CAT) were abolished, reflecting a compromised redox defense system in diabetes." (PMID 41049554, 2025). "Administration of grape pomace extract increased superoxide dismutase activity by 1.4 times and catalase activity by 1.5 times in diabetic animals compared to untreated diabetes." (PMID 41226146, 2025). "We observed a decrease of 1.4 times in both superoxide dismutase and catalase activities in diabetes compared to control group." (PMID 41226146, 2025). "In diabetic cataract rats, the levels of the antioxidant enzymes CAT, GPX, and SOD were significantly decreased, while the expressions of the oxidative stress markers AOPP, GSSG, and TBARS were significantly decreased." (PMID 40635755, 2025).
diabetes (continued). "The possibility of protein-level reductions in other antioxidant enzymes, such as SOD1, SOD2, and catalase, under diabetes distress remains to be explored and constitutes a major limitation of our study." (PMID 41462586, 2025). "Some multicenter and larger cross-sectional investigations demonstrated decreased SOD/GSH-Px or SOD/CAT in diabetes compared with controls, and more recent work with larger samples confirms that reduced SOD/CAT is associated with NPDR and PDR stages." (PMID 41154513, 2025). "Glutathione (GSH) deficiency, reduced synthesis of superoxide dismutase (SOD) observed in patients with diabetes, as well as catalase (CAT) and peroxidase in diabetic rat models contribute to the redox imbalance." (PMID 40904859, 2025). "In our study, streptozotocin-induced diabetic rats exhibited significantly increased catalase levels compared to the control rats, possibly as the body’s initial defense against diabetes-induced oxidative stress." (PMID 40489503, 2025). "Studies in humans and experimental models indicate that superoxide dismutase 2 (SOD 2), glutathione peroxidase (GPx), and catalase activities in the mitochondria decrease due to hyperglycemia in diabetes." (PMID 38792935, 2024). "Both GSH (μmol/g protein) and catalase (ng/g protein) levels were significantly affected by diabetes induction and SITG administration over 30 days." (PMID 39766390, 2024). "marmelos increased the antioxidant levels of superoxide dismutase, catalase, and glutathione peroxidase and decreased the malondialdehyde in a diabetes-induced mouse model." (PMID 39479139, 2024). "Administration of safranal (0.25, 0.50, and 0.75 mg/kg/day, for 28 days) to diabetic rats increased CAT, SOD, and GSH levels in lung tissue and bronchoalveolar lavage fluid (BALF) and therefore protected lung tissue against lung damage caused by diabetes." (PMID 38419885, 2024). "A significant (P<0.05) elevation in MDA level and reduction in SOD and CAT activities in the diabetic group was observed after six weeks of diabetes induction." (PMID 38234664, 2024). "Treatment with SOD/catalase mimics in diabetic mice prevents the oxidative inhibition of aortic procyclin synthase induced by diabetes and normalizes different pathways involved in hyperglycemic injury." (PMID 39674630, 2024). "Diabetes and insulin resistance decrease the levels of antioxidants such as catalase (CAT), glutathione (GSH), and superoxide dismutase (SOD)." (PMID 38233819, 2024). "In an in vitro study, this bitter gourd polysaccharide improved diabetes mice by enhancing the concentration of CAT, SOD, and GSH-px antioxidant enzymes and decreasing the content of MDA in mice." (PMID 37497112, 2023). "In the case of diabetes (group D) and diabetes and periodontitis (PD), the antioxidant capacity was more altered, with CAT levels being significantly lowered compared with those registered in the periodontitis group (P) (p < 0.05)." (PMID 38132422, 2023). "In the diabetes+IE group, the activities of GPx, CAT and SOD were increased compared with the diabetic group." (PMID 37098926, 2023). "Fructose/STZ-induced diabetes resulted in significantly reduced (P < 0.05) glutathione levels and catalase activity in the striatum of untreated diabetic rats as compared to normal rats." (PMID 37441190, 2023). "MP can enhance the levels of antioxidant enzymes such as SOD, GSH-Px, and CAT in diabetes models in vivo." (PMID 37497112, 2023). "The level of GSH and the activities of SOD and catalase enzymes in the cardiac tissues were significantly (p < 0.05) suppressed after the induction of diabetes; this was also accompanied by a marked increase in MDA level." (PMID 35841183, 2023). "The group with diabetes lost 81.55% and 77.73% of their activities of CAT and SOD, respectively, in comparison with the normal control one." (PMID 37280499, 2023).